TRIM64B (tripartite motif containing 64B)
Tractability: No criterion of Open Targets' tractability assessment is met for any kind of drug.
Gene: Protein-coding gene on chromosome 11 (89,870,438 to 89,878,487, reverse strand). Ensembl gene ENSG00000189253.
Gene Ontology:
Molecular function: ubiquitin protein ligase activity; metal ion binding; zinc ion binding
Biological process: innate immune response; regulation of gene expression
Cellular component: cytoplasm
Genetic constraint (gnomAD): Loss-of-function variants: 0 observed, 25.29 expected, observed/expected ratio (o/e) 0, 90% interval 0 to 0.12. The synonymous counts are far from expectation, so gnomAD's model fits this gene poorly and the ratio says little. Missense variants: 50 observed, 311.3 expected, observed/expected ratio (o/e) 0.16, 90% interval 0.13 to 0.2. Synonymous variants: 16 observed, 102.09 expected, observed/expected ratio (o/e) 0.16, 90% interval 0.1 to 0.24.
Homologues: Paralogues in human: TRIM64 (98% identical), TRIM64C (91% identical), TRIM43 (47% identical), TRIM43B (47% identical), TRIM51 (47% identical), TRIM49 (46% identical), TRIM49C (46% identical), TRIM49B (46% identical), TRIM49D1 (44% identical), TRIM49D2 (44% identical), TRIM51G (44% identical), TRIM77 (41% identical), and 68 more.